TEX11 (testis expressed 11)
Description:
Regulator of crossing-over during meiosis. Involved in initiation and/or maintenance of chromosome synapsis and formation of crossovers.
Synonyms: ZIP4H; ZIP4; TSGA3; TGC1; MZIP4; Spo22; SPGFX2
Tractability: No criterion of Open Targets' tractability assessment is met for any kind of drug.
Gene: Protein-coding gene on chromosome X (70,528,940 to 70,908,711, reverse strand). Ensembl gene ENSG00000120498.
Subcellular location: Chromosome
Gene Ontology:
Molecular function: protein binding
Biological process: homologous chromosome pairing at meiosis; male meiosis chromosome segregation; meiotic DNA double-strand break formation; meiotic gene conversion; reciprocal meiotic recombination; resolution of meiotic recombination intermediates; spermatogenesis; synaptonemal complex assembly; meiotic cell cycle
Cellular component: central element; chromosome; recombination nodule; synaptonemal complex; condensed nuclear chromosome
Homologues: Orthologues: chimpanzee TEX11 (97% identical), macaque TEX11 (94% identical), dog TEX11 (73% identical), pig TEX11 (71% identical), rabbit TEX11 (63% identical), rat Tex11 (56% identical), mouse Tex11 (55% identical), tropical clawed frog tex11 (47% identical), zebrafish tex11 (46% identical).
Diseases named in the same sentence as TEX11 in open-access papers:
TEX11 is named in the same sentence as 18 diseases in open-access papers, as found by Europe PMC text mining. Sharing a sentence is not in itself a finding about the gene and the disease. The quoted sentences say what the papers report.
Azoospermia (24 papers, 2015 to 2025). Absence of any measurable level of sperm,whereby spermatozoa cannot be observed even after centrifugation of the semen pellet. "The discovery of TEX11 mutations has stimulated interest in the underlying causes of azoospermia in general and of meiotic arrest in particular." (PMID 39231187, 2024). "Evidence indicated that TEX11 gene is involved in chromosomal synapsis and meiotic recombination and can cause to oligozoospermia, azoospermia, meiotic arrest, and male infertility." (PMID 35248021, 2022). "Since then, additional TEX11 missense variants or deletions have been reported [47,4852,53]; suggesting that this X-linked gene has a major role on azoospermia." (PMID 33882832, 2021). "TEX11 is enriched in late spermatocytes and spermatids in mice, disruption of which in knock-out mice causes meiotic arrest and azoospermia." (PMID 34621296, 2021). "We found that TEX11 mutations in infertile men are important for the diagnosis of azoospermia and meiotic arrest." (PMID 34621296, 2021). "The gene is highly expressed in late spermatocytes and in spermatids in mice, and disruption of Tex11 in knock-out mice causes meiotic arrest and results in azoospermia." (PMID 31875237, 2021). "TEX11 (on Xq13.1) is currently the most frequently reported gene as being associated with azoospermia." (PMID 33882832, 2021). "TEX11 (on Xq13.1) is currently the gene most frequently reported as being associated with azoospermia." (PMID 33882832, 2021). "This study and previous literature indicate that TEX11 mutations are closely associated with male infertility, especially azoospermia, although auxiliary clinical analyses are needed to figure out the causes of male infertility." (PMID 29661171, 2018). "This study reported one novel TEX11 mutation (2653G → T, in exon 29, GenBank accession number, NM_031276) in two brothers with azoospermia." (PMID 29661171, 2018). "Given the high incidence of TEX11 mutations, this gene could be a significant candidate for the clinical evaluation of azoospermia." (PMID 37124723, 2023). "Mutations of TEX11 reported for azoospermia patients in published literature and our data." (PMID 37124723, 2023). "Furthermore, a custom panel for detecting the known genes of azoospermia was developed, from which three cases with positive results (two with TEX11 mutation, one with AR mutation) were excluded." (PMID 35495142, 2022). "Several studies have shown that Tex11 is strongly associated with azoospermia in human males." (PMID 36091389, 2022). "Furthermore, the X chromosome houses one of the most compelling candidate genes for recombination rate, i.e. TEX11, a meiosis gene that evolves rapidly in vertebrates and is associated with azoospermia and failure of meiotic synapsis in humans and mice." (PMID 34171988, 2021). "Thus, hemizygous mutations in the TEX11 are to date the first X‐chromosomal and major single gene defect in azoospermia." (PMID 29527098, 2018). "They identified the loss of three TEX11 exons (exons 10–12) in two patients with azoospermia and five novel TEX11 mutations (three splicing mutations and two missense mutations) in 7 of 289 (2.4%) men with azoospermia." (PMID 29661171, 2018). "Moreover, another recent study screened for mutations in the TEX11 open reading frame in 289 patients with azoospermia and 384 controls." (PMID 29661171, 2018). "Disruption of Tex11 gene function causes meiotic arrest in males, resulting in azoospermia." (PMID 26136358, 2015). "Miscellaneous variants in CATSPER1, SPATA16, and TEX11 genes are identified that play important roles in pathogenesis of sperm morphology (teratozoospermia), sperm motility parameters (asthenozoospermia), or sperm number (oligozoospermia or azoospermia) in human." (PMID 35248021, 2022).
Azoospermia (continued). "The TEX11 mutations may disturb the formation and function of the synaptonemal complex, causing major disruption of pachytene synapsis and anaphase spindle checkpoints, which, in turn, triggers meiotic arrest, spermatocyte apoptosis, and azoospermia." (PMID 34621296, 2021). "An exome-based panel targeting genes strongly linked to male infertility (including AR, DMRT1, M1AP, TEX11, and NR5A1) has demonstrated a diagnostic yield of 8.5% in previously unexplained cases of azoospermia." (PMID 41401169, 2025). "The aim of this study was to investigate association of idiopathic azoospermia and oligospermia with single-nucleotide polymorphisms of CATSPER1, SPATA16 and TEX11 genes in Iranian-Azeri men." (PMID 35248021, 2022). "Other genes related to male infertility were identified to associate with azoospermia (e.g., SOHLH1, SYCP3, and TEX11)." (PMID 34442404, 2021). "Although TEX11 and ADGRG2 defects are frequently described in men with azoospermia, most of the causal gene defects found to date are private (i.e. identified in a small number of consanguineous families)." (PMID 31024732, 2019). "The structural defect in the murine TEX11 protein was not sufficient to cause the defect of azoospermia." (PMID 39231187, 2024). "In the present study, we reported three novel TEX11 mutations in the patients with severe non-obstructive azoospermia and analyzed the genetic causes by WES." (PMID 37124723, 2023). "Testis-expressed gene 11 (TEX11) mutation has been associated with non-obstructive azoospermia (NOA) and meiotic arrest." (PMID 34621296, 2021). "Forty variants were subsequently identified by sequencing TEX11 exons 2 to 30 and the flanking intronic regions in a large cohort of infertile men with nonobstructive azoospermia (n = 246) and in fertile controls (n = 175)." (PMID 33882832, 2021). "Together, these data provide strong evidence that LoF variants in TEX11 cause non-obstructive azoospermia due to meiotic arrest also in human males." (PMID 31875237, 2021). "In contrast, the testes of the patients who suffered from azoospermia with TEX11 mutations showed meiotic arrest and lacked TEX11 expression." (PMID 29259455, 2017). "Here, we report that TEX11 is mutated in infertile men with non-obstructive azoospermia and that an analogous mutation in the mouse impairs meiosis." (PMID 26136358, 2015). "Interestingly, the association of TEX11 mutations with human infertility (non-obstructive azoospermia) is well characterized." (PMID 30272023, 2018). "Next-generation sequencing has contributed to the identification of several unknown genetic alterations in the context of male infertility and azoospermia including FANCA, PLK4, WKN3, MEI1, ADAD2, and TEX11." (PMID 40747475, 2025). "Therefore, this study aimed to replicate this finding in humans byexamining the expression levels of TEX11, TEX12,TEX14, and TEX15 in the testis tissue of patients withnon-obstructive azoospermia and comparing them against controls." (PMID 29932616, 2018). "In the first step of this study, high-resolution array-CGH was used to screen men with non-obstructive azoospermia, revealing a recurring deletion of three exons of TEX11 in two patients." (PMID 29527098, 2018).
male infertility (20 papers, 2015 to 2025). The inability of the male to effect fertilization of an ovum after a specified period of unprotected intercourse. "After chromosomal abnormalities and Y chromosome microdeletions, TEX11 defects are now considered to be the third most frequent cause of male infertility (in 2–3% of infertile men)." (PMID 41300722, 2025). "In recent years, two studies extensively investigated TEX11 gene polymorphisms correlation with male infertility." (PMID 35248021, 2022). "We identified one novel TEX11 mutation in two brothers and summarized the literature regarding TEX11 mutations and male infertility." (PMID 29661171, 2018). "TEX11 deficiency causes meiotic arrest and male infertility, and many TEX11 mutations have been found in azoospermic and infertile men." (PMID 29661171, 2018). "Additionally, the coiled-coil domain of murine SYCP2 interacts with SYCP3 and TEX11, which are themselves implicated in human male infertility." (PMID 39202451, 2024). "Tex11-deficient spermatocytes mostly undergo apoptosis at the pachytene stage, while surviving cells display chromosome nondisjunction at the first meiotic division - causes cell death and male infertility." (PMID 33882832, 2021). "However, up to now, for only three genes, i.e., NR5A1, DMRT1, and TEX11, associations with male infertility have been evidenced in independent biological and functional studies." (PMID 31963602, 2020). "The authors also reported thatthe level of TEX11 protein must be above a critical threshold formeiosis to progress, and that low-expressing TEX11 alleles may thusresult in human male infertility." (PMID 29932616, 2018). "TEX11-deficient spermatocytes mostly undergo apoptosis at the pachytene stage, while survived cells display chromosome nondisjunction at the first meiotic division, which causes cell death and male infertility." (PMID 29661171, 2018). "Additionally, single nucleotide polymorphisms (SNPs) have a major impact in percentage of normal sperm, SNPs in TEX11 gene showed close association with idiopathic male infertility." (PMID 29661171, 2018). "In addition, we summarized the mutations of TEX11 related to male infertility." (PMID 37124723, 2023). "In addition, we summarized the literature regarding TEX11 mutations and male infertility." (PMID 29661171, 2018). "A Tex11-/- mouse line (with deletion of exons 3 to 29 out of the 30 in the mouse) showed male infertility due to meiotic arrest, chromosomal asynapsis at the pachytene stage, and reduced crossover formation." (PMID 39231187, 2024). "In existing studies, SYCP2 was reported as a robust candidate gene for male infertility since its encoding protein can interact directly with protein products of the male infertility genes TEX11 and SYCP3 in mice." (PMID 36159998, 2022). "There are also male infertility cases caused by defects in single genes including CFTR, DDX3Y, SYCP3, TEX11, AURKC, and DPY19L2, but the number of genes confidently linked to male infertility remains very low." (PMID 34190021, 2022). "We investigated the genetic causes of male infertility in a cohort of 479 patients with NOA using WES, and pathogenic variants of TEX11 were identified in 14 patients (four sporadic and 10 from three families)." (PMID 34621296, 2021). "In this literature review, we mainly discuss the dominant effects of TEX11 on spermatogenesis and male infertility." (PMID 29661171, 2018). "Taken together, we conclude that the autosomal Tex11 KI minigene rescues meiotic arrest and male infertility in adult Tex11−/Y mice." (PMID 26136358, 2015). "Indeed, TEX11 is one such X-chromosomal gene with an o/e fraction of zero and one of the best established male infertility genes." (PMID 40624043, 2025). "To date, association of CATSPER1 (rs2845570), SPATA16 (rs1515442), and TEX11 (rs143246552) genes polymorphism and male infertility was not investigated in Iranian Azeri population." (PMID 35248021, 2022).
male infertility (continued). "Therefore, different expression levels of TEX11 or single amino acid substitutions may contribute to the variable genome-wide meiotic recombination rates between sexes and among individuals, and as such, low-expressing TEX11 alleles could be genetic causes of male infertility in humans." (PMID 26136358, 2015). "However, no study has been reported on effect of TEX11 rs143246552 polymorphism on male infertility." (PMID 35248021, 2022).
Infertility (18 papers, 2015 to 2025). "The results of physical examinations showed that the infertile patients with pathogenic variants in TEX11 were healthy." (PMID 34621296, 2021). "These include, for example, multiple DNA repair genes linked to infertility and various cancers and TEX11, which is expressed in the testis and the pancreas according to RNA-seq data (GTEx Portal)." (PMID 34498060, 2021). "Genetic screening of a large cohort of idiopathic infertile men reveals that TEX11 mutations, including frameshift and splicing acceptor site mutations, cause infertility in 1% of azoospermic men." (PMID 26136358, 2015). "Significantly, our results strongly support that the human TEX11 V748A mutation is likely a genetic cause of infertility in azoospermic men." (PMID 26136358, 2015). "We find that the engineered Tex11 minigene on the autosome rescues the infertility caused by the X-linked Tex11 deletion." (PMID 26136358, 2015). "In combination with analyses of genetically modified mice harboring Tex11 mutations analogous to those in human, our results demonstrate that in ∼1% of azoospermic men, infertility is caused by mutations in a single X-linked gene—the TEX11 gene." (PMID 26136358, 2015). "Fourthly, the human infertility phenotype might result from the variant’s effects on TEX11 expression." (PMID 41300722, 2025). "Even though the presence of the in frame TEX11-c.652del237bp variant might well explain the infertility of the three patients described in the literature, another genetic etiology would have to be ruled out with WES or WGS." (PMID 41300722, 2025). "Fourthly, the infertility phenotype might depend on the effect of the human variant on TEX11 protein expression." (PMID 39231187, 2024). "TEX11 (rs6525433) displayed mutations in only two of eight infertile men." (PMID 37895049, 2023). "Testis-expressed gene 11 (TEX11) is a germ cell-specific gene, and the formation of crossovers and mutations in the TEX11 gene may be a genetic cause of infertility in men." (PMID 34944753, 2021). "Moreover, mutations or partial deletions of some X-linked genes such as AKAP3, AKAP4, NXF2, TAF7L, USP26, and TEX11 are linked to male subfertility or infertility." (PMID 29661171, 2018). "Recently, X-linked TEX11 mutations have been observed in infertile men." (PMID 29661171, 2018). "We next determined whether the wild-type autosomal Tex11 knockin minigene (Tex19Tex11KI) could functionally replace its X-linked progenitor and rescue infertility of azoospermic Tex11−/Y males." (PMID 26136358, 2015). "A conservative calculation that considers only three TEX11 mutations (frameshift mutation in exon 16, splice site mutation in intron 21, and V748A missense mutation) indicates an infertility-causing mutation frequency in human TEX11 of ∼1% (three mutations/246 azoospermic men screened)." (PMID 26136358, 2015). "The mutations at the SNPs of TEX11 (rs4844247), LHB (rs4146251380), USP26 (rs61741870) and (rs41299088), and ANOS1 (rs2229013) were displayed in only one of eight infertile men." (PMID 37895049, 2023). "By using NGS technologies to perform more unbiased genomic studies, we identified infertility-associated mutations of numerous genes (e.g., SYCP2, SYCP3, and TEX11)." (PMID 34621296, 2021). "Thanks to high-throughput approaches such as whole exome sequencing (WES) and comparative genomic hybridization (CGH) arrays, novel X-linked gene mutations (e.g., TEX11 and ADGRG2) have been discovered as causative factors of different infertile phenotypes." (PMID 31875237, 2021). "Recently, an intragenic TEX11 deletion removing exons 10–12 was identified by high-resolution X-specific array-CGH in two infertile patients with NOA due to meiotic arrest and mixed testicular atrophy, respectively." (PMID 31875237, 2021). "This study presents three novel variants of TEX11 as potential infertility alleles that have not been previously reported." (PMID 37124723, 2023).
Infertility (continued). "Finding a high mutation frequency of TEX11 among infertile men is not entirely unexpected: TEX11 is X-linked, such that any inherited or de novo mutations that impair the function of this essential fertility factor would manifest as infertility." (PMID 26136358, 2015). "Functional evaluation of three analogous human TEX11 missense mutations in transgenic mouse models identified one mutation (V748A) as a potential infertility allele and found two mutations non-causative." (PMID 26136358, 2015). "While the identification of the TEX11-c.652del237bp variant might explain an infertility phenotype, its presence should not constate a strict contraindication to TESE." (PMID 41300722, 2025). "However, it is noteworthy that the functional evaluation of three analogous human TEX11 missense mutations in transgenic mouse models identified one mutation (V748A) as a potential infertility allele and two mutations as non-causative." (PMID 34621296, 2021). "Another study revealed that TEX11-null mice may show elimination of spermatocytes and infertility." (PMID 34439962, 2021). "Stage-specific expression ofTEX11 in porcine meiotic germ cells is in agreement withfindings in mice, where the lack of Tex11 disturbs the progressionof meiosis and thus results in infertility." (PMID 29932616, 2018). "In view of our results and the literature data on TEX11 mutations, one can hypothesize that genetic alterations in the SPO22 domain lead to infertility only if the variant lead to the total absence of protein expression." (PMID 39231187, 2024).
colorectal cancer (2 papers, 2022 to 2025). A primary or metastatic malignant neoplasm that affects the colon or rectum. "TEX11 has been regarded as a potential biomarker for early-onset colorectal cancer (CRC) based on database analyses." (PMID 41459538, 2025). "Considering that genetic instability is a critical factor for the initiation of colorectal cancers, the reduced expression of TEX11 may lead to the impairment of DSB repair machinery." (PMID 36319719, 2022).
spermatogenic failure (2 papers, 2015 to 2021). A male infertility characterized by dirsuption of the process of sperm development from diploid cells into mature haploid spermatozoa. "A screen of genomic samples from 246 azoospermic men with spermatogenic failure (no sperm in semen) found a significantly high prevalence of singleton variants in azoospermic men (7.3%), suggesting that TEX11 is required for spermatogenesis in human." (PMID 34621296, 2021).
oligoasthenoteratozoospermia (1 paper, 2021). A form of male infertility that is characterized by a combination of low number or oligozoospermia, poor motility or asthenozoospermia, and abnormal shape or teratozoospermia of sperms. "The allele (T) of the TEX11 gene led to the development of oligoasthenoteratozoospermia, a severe disorder of spermatogenesis." (PMID 34178030, 2021).